TOP6BL (TOP6B like initiator of meiotic double strand breaks)
Description:
Non-catalytic component of a topoisomerase 6 complex specifically required for double-strand breaks (DSB) formation that initiate meiotic recombination. Together with SPO11, mediates DNA cleavage that forms the double-strand breaks (DSB) that initiate meiotic recombination (By similarity). The complex promotes relaxation of negative and positive supercoiled DNA and DNA decatenation through cleavage and ligation cycles (By similarity). Within the complex, TOP6BL may sense specific DNA architectures, such as bendable and underwound DNA for cleavage by SPO11 (By similarity).
Synonyms: TOPOVIBL; C11orf80; FLJ22531; HYDM4
Tractability: PROTAC: ubiquitination databases record sites on it.
Gene: Protein-coding gene on chromosome 11 (66,744,451 to 66,843,516, forward strand). Ensembl gene ENSG00000173715.
Subcellular location: Chromosome; Nucleus
Subcellular location (Human Protein Atlas): Centrosome
Gene Ontology:
Molecular function: DNA secondary structure binding
Biological process: meiotic DNA double-strand break formation; reciprocal meiotic recombination
Cellular component: chromosome; DNA topoisomerase type II (double strand cut, ATP-hydrolyzing) complex; nucleus
Genetic constraint (gnomAD): Loss-of-function variants: 38 observed, 43.04 expected, observed/expected ratio (o/e) 0.88, 90% interval 0.68 to 1.16. The upper end of that interval is the gene's LOEUF score, 1.16, which puts it in group 5 of 6, group 1 being the genes least tolerant of losing a copy. Missense variants: 531 observed, 508.28 expected, observed/expected ratio (o/e) 1.04, 90% interval 0.97 to 1.12. Synonymous variants: 215 observed, 190.64 expected, observed/expected ratio (o/e) 1.13, 90% interval 1.01 to 1.26.
Homologues: Orthologues: chimpanzee TOP6BL (99% identical), pig TOP6BL (69% identical), rat Top6bl (64% identical), mouse Top6bl (64% identical), macaque TOP6BL (56% identical), dog TOP6BL (25% identical), zebrafish zgc:195212 (19% identical).
Diseases named in the same sentence as TOP6BL in open-access papers:
TOP6BL is named in the same sentence as 5 diseases in open-access papers, as found by Europe PMC text mining. Sharing a sentence is not in itself a finding about the gene and the disease.
TOP6BL shares sentences with these, for which no sentence is quoted: cancer (1 paper); Headache (1); migraine (1); mood disorder (1); recurrent hydatidiform mole (1).